CCR2 (C-C motif chemokine receptor 2)
Diseases named in the same sentence as CCR2 in open-access papers (continued):
Sharing a sentence is not in itself a finding about the gene and the disease.
atherosclerosis (continued). "The contribution of sexual dimorphism in synergy with monocyte subpopulations expressing CCR2 to the development of atherosclerosis, since early ages is still unclear." (PMID 36286282, 2022). "We are now working on increasing the number of children enrolled in the study to clarify the contribution of circulating monocytes expressing CCR2 and other chemokine receptor repertoires to atherosclerosis development in a sex-dependent fashion." (PMID 36286282, 2022). "The differential contribution of monocyte subsets expressing the C-C chemokine receptor 2 (CCR2) to subclinical atherosclerosis in girls and boys is unclear." (PMID 36286282, 2022). "Many studies in both humans and animals have shown the importance of MC chemoattractant protein-1 (MCP-1, also named CCL2) and its receptor CCR2 in pathologies, such as atherosclerosis." (PMID 34987524, 2021). "Till now, several small interfering RNAs (siRNAs), monoclonal antibodies, and antagonists for CCR2 have been designed and shown promising efficiency on atherosclerosis therapy." (PMID 34345249, 2021). "Growing evidence suggests that aberrant CCR2 activation by monocyte chemoattractant proteins can induce atherosclerosis (Colin, Chinetti-Gbaguidi & Staels, 2014), insulin resistance and several types of malignant tumor." (PMID 34754619, 2021). "In all, blocking monocyte recruitment via CCR2 seems to be an effective strategy in atherosclerosis progression." (PMID 34345249, 2021). "In this sense, elevated circulating nLDL levels are associated with an increment in the percentage of CMs that can migrate into endothelial tissue by mainly expressing CX3CR1 and CCR2 in ApoE−/− mice, an animal model of atherosclerosis." (PMID 34439835, 2021). "Understanding the pathophysiology of atherosclerosis, it was observed that CC chemokine receptor 2 (CCR2) tends to be highly expressed on inflammatory cells and in the atherosclerotic plaques." (PMID 33799932, 2021). "Accumulated evidence supports the notion that CCL2 and its receptor CCR2 participate in cancer metastasis, inflammation disease, obesity and atherosclerosis." (PMID 34754619, 2021). "Our results documenting reduced expression of CCR2 and SIRP-α on inflammatory monocytes due to TRAM deficiency further provide a mechanistic basis underlying reduced pathogenesis of atherosclerosis in TRAM-deficient mice." (PMID 34499622, 2021). "Reducing macrophage recruitment by silencing chemokine (C–C motif) receptor 2 (CCR2) expression is a promising therapeutic approach against atherosclerosis." (PMID 33184330, 2020). "Recruitment of inflammatory monocytes has been studied in the pathogenesis of atherosclerosis; however, recent studies revealed that monocytes with CCR2 expression are recruited not only to atherosclerotic plaque but also to ventricular myocardium." (PMID 33048984, 2020). "In particular, in atherosclerosis and myocardial infarction models, the use of siCCR2 and CCR2 KO mice resulted in a smaller necrotic area and delayed debris clearance with no occurrence of regression." (PMID 33664739, 2020). "In our experiment, the level of CCR2 in macrophages increased dramatically under the stimulation of oxLDL, which also proved the close relationship between CCR2 and hyperlipideamia in atherosclerosis." (PMID 33184330, 2020). "Another research shows that in atherosclerosis regression animal models, deficiency of CCR2 or CX3CR1, but not CCR5, prevents plaque regression and acute inhibition of CCR2 prevents plaque regression and suppresses enrichment in the M2 macrophage phenotype." (PMID 30923552, 2019). "The affinity of CCTV to CCR2 in inflammatory atherosclerosis enables imaging and suggests promise for long-term benefits on plaque pathology." (PMID 31723548, 2019).
atherosclerosis (continued). "We demonstrate that CCTV target the IL-1β pathway upstream, while its high affinity to CCR2 allowed for atherosclerosis delivery and imaging." (PMID 31723548, 2019). "The involvement of CCR2 in pathologies such as atherosclerosis has resulted in many efforts to develop biologic and small molecule antagonists targeting this receptor." (PMID 28246398, 2017). "A number of studies have demonstrated that genetic deletion of CCL2 or CCR2 slowed the disease course in animal models of atherosclerosis." (PMID 27458015, 2016). "In cardiovascular disease in particular, there is evidence that multiple CC-CK and their receptors act in concert to promote atherosclerosis, since CCR2−/−, CCR5−/− and CCL2−/− mice have all shown reduced atherosclerosis in hyperlipidemic models." (PMID 25077938, 2014). "CCR2(-/-) mice show defect in monocyte recruitment and decreased atherosclerotic lesions, indicating the important role of CCR2 in the development of atherosclerosis." (PMID 25411969, 2014). "Altogether, these data suggest that the MS diet ameliorates development of atherosclerosis by inhibiting the T-cell Ccr2 expression, reducing inflammatory cytokines production and increasing serum HDL:LDL ratio." (PMID 23437105, 2013). "The CC chemokines, which contain two adjacent cysteines near the amino terminus, are particularly important, and the role of CCL2, a ligand for CCR2, in the development of atherosclerosis has been substantiated in animal models and humans." (PMID 23659629, 2013). "The nuclear receptor PPAR-γ has the inherent capacity to regulate expression of macrophage chemokine receptors (CX3CR1 and CCR2) in lipid-mediated inflammation in atherosclerosis lesions." (PMID 22815945, 2012). "Mice, deficient in MCP-1 or its receptor CCR2, had significantly reduced atherosclerotic lesions, suggesting that MCP-1/CCR2 interaction has a role in monocyte recruitment in atherosclerosis." (PMID 21772662, 2011). "Further evidence for the role of CCL2 and its receptor CCR2 in the pathology of atherosclerosis has come from gene knock-out experiments in mice." (PMID 20181074, 2010). "Several lines of evidence support a role for CCL2 (monocyte chemotactic protein-1) and its receptor CCR2 in the development of atherosclerosis." (PMID 20181074, 2010). "Taken together, these studies strongly suggest a direct role for CCL2 and CCR2 in monocyte recruitment and in the pathology of atherosclerosis." (PMID 20181074, 2010). "Based upon previous work implicating the CCR2 gene in the progression of atherosclerosis, we sought to further assess the role of the Val64Ile polymorphism in the clinical endpoint of coronary artery disease." (PMID 20181074, 2010). "The result with CCR2 extends the substantial evidence for its involvement in mouse atherosclerosis, but with a possible greater role in monocyte arrest." (PMID 18579408, 2008). "Our results indicate that combining antimicrobials with CCR2 immunomodulation may reduce mycobacteria-aggravated atherosclerosis." (PMID 41987917, 2026). "Correspondingly, interventions targeting monocyte recruitment by disrupting MCP-1/CCL2 (monocyte chemoattractant protein 1) and CCR2 signaling have shown promise in mitigating excessive inflammation and conferring protection in mouse models of myocardial infarction and atherosclerosis." (PMID 40257974, 2025). "Preclinical data suggest that pharmacological targeting of CCL2 or its receptor CCR2 might lower atherosclerosis burden in experimental models." (PMID 40119478, 2025). "The MCP-1/CCR2 axis plays a pivotal role in directing monocyte migration towards sites of inflammation, acting as a crucial mediator in various pathological conditions such as atherosclerosis and cancer." (PMID 40257974, 2025). "In addition, the CCL2 receptor CCR2 is expressed on classical and intermediate monocytes and is key in establishing atherosclerosis in mice models." (PMID 38247848, 2024).
atherosclerosis (continued). "Although these studies support a role of the CCL2/CCR2 axis in human atherosclerosis, it remains unclear whether pharmacological intervention in this pathway could lead to atheroprotection in humans." (PMID 37645892, 2024). "Thus, inhibiting glucose metabolism promoted monocyte recruitment during atherosclerosis progression and increased their CCR2 expression." (PMID 39424804, 2024). "CCR2 is a key chemokine receptor for monocyte recruitment at earlystage of atherosclerosis and is decreased by GDF-15–deficient macrophages.The direct interaction of GDF-15 with the chemokine receptor CCR2 functionsuggests that the GDF-15-induced macrophage mobility modulates the CCR2 response." (PMID 39077481, 2023). "In a preclinical model, CCL2-CCR2 was identified as being crucial in the development of atherosclerosis such that the selective deletion of CCR2 significantly decreased atherosclerotic lesions and was associated with a reduced accumulation of monocytes/macrophages." (PMID 36498974, 2022). "In addition, clinical trials on CCR2 inhibition have focused on diabetes, multiple sclerosis, atherosclerosis, and childhood interstitial pneumonia." (PMID 36566220, 2022). "Thus, species-specific mechanisms, including, e.g., the observed discrepancies in the atherosclerosis development pathway involving CCR2 and CXCR4 signaling, should be taken into account in future research." (PMID 35737302, 2022). "In an ApoE−/− high-fat diet murine model of atherosclerosis, delivery of a small molecule CCR2 antagonist showed significant decrease in plaque size and lesional macrophage numbers only in mice treated at ZT17 but not when the same antagonist was applied at ZT5." (PMID 36339576, 2022). "Moreover, CCL2 and its receptor CCR2 are important mediators of macrophage accumulation in atherosclerotic lesions, which are considered targets to inhibit the progression of atherosclerosis." (PMID 35990936, 2022). "The CCR2 expression was 16.1% ± 6.5% higher in intermediate monocytes from boys with IMT ≥ p75 than in male children without subclinical atherosclerosis risk (p = 0.047)." (PMID 36286282, 2022). "The rs17735770 genetic variant led to increased expression of CCL7, a potential antagonist of CCR2 at inflammatory sites, where it could play a meaningful role during the evolution of atherosclerosis." (PMID 35711383, 2022). "Interestingly, expression of CCR2 has been shown to play a critical role in atherosclerosis development." (PMID 35900662, 2022). "CCR2 was identified as a genetic determinant of atherosclerosis in mice." (PMID 36110847, 2022). "Results from our study showed that expression of CCR2 and CCL2 on the mRNA level was shown only in atherosclerotic patients with non-fatal ACS, thus confirming the association of PMAs formation with atherosclerosis and ACS." (PMID 35563407, 2022). "Both Ccr2 and Ccl2 knockout in atherosclerosis-prone mice as well as Ccr2 targeted siRNA treatment significantly reduced atherosclerotic plaque formation, whereas in contrast, leukocyte-specific overexpression of Ccl2 in Apoe−/− mice promoted atherosclerosis progression." (PMID 35087886, 2021). "In according to this, atherosclerosis models like CCL2 gene knock out in LDL receptor–deficient mice or CCR2 deprivation models generated by crossing mice that lack CCR2 with apo E-null mice which develop severe atherosclerosis showed a promising effect on atherosclerosis prevention." (PMID 34345249, 2021). "After one week, the expression in the chemokine receptors CXCR4, CCR8, CCR5, and CCR2, which are all known to play an important role in inflammation and atherosclerosis development, was analyzed on the surface of various leukocyte subsets in the blood and spleen using flow cytometry." (PMID 34884827, 2021). "The proinflammatory marker CCR2 was reduced in 3GA-494-treated atherosclerosis-prone mice." (PMID 34853722, 2021). ".c, 4 weeks) induced atherosclerosis and aneurysm in ApoE−/− CCR2−/− and ApoE−/− CCR2+/+ mice." (PMID 34489714, 2021).
atherosclerosis (continued). "With their low cytotoxicity and efficient drug delivery, ENP could be a useful carrier for target delivery of CCR2-shRNA to inflammatory monocytes/macrophages for the therapy against atherosclerosis." (PMID 33184330, 2020). "In our study, we observed a correlation between splenic activity and CCR2 expression on circulating HSPCs which might suggest that the spleen performs a role in human atherosclerosis." (PMID 33168134, 2020). "The results suggest that CCR2 shRNA encapsulated ENP’s might be used to reduce the migration of macrophage in atherosclerosis by down regulation of CCR2 level." (PMID 33184330, 2020). "Second, as the cellular model in our experiment is mimicking mature foam cells, the effect of CCR2-shRNA ENPs to an early stage atherosclerotic monocytes is to be studied, which might be important for the prevention and early therapy of atherosclerosis." (PMID 33184330, 2020). "In this study, we aimed to evaluate the binding kinetics and pharmacokinetics of 15a for murine CCR2 (mCCR2) and determine whether this CCR2 antagonist is effective in an apoE−/− mouse model of atherosclerosis." (PMID 28246398, 2017). "In this report, we aimed to determine whether 15a, an antagonist with a long residence time on the human CCR2, is effective in inhibiting the development of atherosclerosis in a mouse disease model." (PMID 28246398, 2017). "Along these lines, the incidence of both atherosclerosis and of aortic aneurysms is significantly reduced in Apo-E deficient mice lacking CCR2, a critical receptor that directs influx of macrophages and T cells to sites of tissue injury." (PMID 26925344, 2016). "Ly6chi monocytes and Mo-MDSCs traffic from the bone marrow (BM) to sites of inflammation via CCR2-signaling, and therapeutic strategies based on CCR2-siRNA showed significant reduction in inflammatory monocyte effects in murine models of atherosclerosis, cancer, and diabetes." (PMID 25982370, 2015). "Furthermore, we have shown a significant inhibition of MCP-1 and its receptor CCR2, the chemokine pathway induced by AngII that contributes to macrophage recruitment and acceleration of atherosclerosis." (PMID 24466075, 2014). "Our data show that a prenatal diet rich in methyl donors significantly retarded the pathogenesis of atherosclerosis in F1 mice through complementary mechanisms, by increasing DNA methylation of T cells, down-regulating the key chemokine receptor CCR2 and shifting the HDL:LDL serum cholesterol level." (PMID 23437105, 2013). "In addition, during atherosclerosis, recruitment of monocytes to atherosclerotic plaque relies on CCR2, CX3CL1/CX3CR1 and CCR5, showing that multiple receptors can be used to recruit these cells to inflammation sites." (PMID 23554169, 2013). "Therefore, the present study aimed to investigate the potential role of H2S in atherosclerosis and the underlying mechanism with respect to chemokines (CCL2, CCL5 and CX3CL1) and chemokine receptors (CCR2, CCR5, and CX3CR1) in macrophages." (PMID 22815945, 2012). "Among a number of chemokines implicated in atherosclerosis, MCP-1 (i.e., CCL2) is the key chemokine responsible for accumulation of inflammatory cells in atherosclerotic lesions after interaction with its receptor CCR2." (PMID 22428064, 2012). "In HIV-infected patients, genetic variations in the CCL2/CCR2 pathway have been associated with survival, and polymorphisms that increase the expression of CCL2 have been repeatedly associated with the presence of subclinical atherosclerosis." (PMID 22645407, 2012). "Ly6C+ monocytes are recruited to mouse atherosclerosis via CCR2, CCR5 and CX3CR1." (PMID 21526997, 2011). "Furthermore, MCP-1 and RANTES play a role in the early progression of atherosclerosis by induction of transendothelial migration via CCR2 and CCR5 chemokine receptors." (PMID 19781706, 2010). "Other evidence attributing a role for CCR2 in the development of atherosclerosis has been shown." (PMID 20181074, 2010).
atherosclerosis (continued). "However, recent studies using transgenic mouse models of atherosclerosis have provided convincing evidence that CCR2 is required for disease progression in apolipoprotein E-null mice." (PMID 16259633, 2005). "Therefore, the PG modulation of the CCL2/CCR2 pathway may be a safe and useful therapeutic strategy for the prevention of atherosclerosis." (PMID 39125901, 2024). "Chemokine-receptor profiling in T1D group was marked by a positive association between CCR2+ monocytes and CCR4+ T lymphocytes with DBP, as well as between CCR2+ and CXCR3+ B lymphocytes with TG, linking endothelial inflammation, atherosclerosis and dyslipidemia." (PMID 39109081, 2024). "We encourage other research teams to assess whether the interaction between monocyte subsets expressing CCR2 and insulin resistance, as surrogate markers of subclinical atherosclerosis, can help understand the development of subclinical atherosclerosis early in life." (PMID 36286282, 2022). "Hence, targeting the transcriptomic profiling of CCR2 could pave the way for effective therapeutics in atherosclerosis management." (PMID 33799932, 2021). "In addition, CCR2 is related to the occurrence of atherosclerosis." (PMID 32258142, 2020). "In summary, our data demonstrate that CCR2-shRNA loaded ENP could be effectively up taken by atherosclerotic cellular model of macrophages and target-silence their CCR2 mRNA expressions, which suggests the nanoparticle’s potential application for therapy of atherosclerosis." (PMID 33184330, 2020). "Several studies involving genetic deletion of CCR2 or MCP-1, and antibody neutralization studies of MCP-1 have clearly established the critical role of the CCR2/MCP-1 axis in mediating several key pathogenic events in animal models of multiple sclerosis and atherosclerosis." (PMID 16001983, 2005). "In animal studies, the levels of MCP-1 and its receptor on monocytes, C-C chemokine receptor type 2 (CCR2), correlate closely with the severity of atherosclerosis and the degree of macrophage accumulation within the plaques." (PMID 40429291, 2025). "Deleting CCL2 or CCR2 in murine models reduced atherosclerotic development and diminished macrophage deposit within plaques, while overexpression of CCL2 enhanced atherosclerosis." (PMID 38892201, 2024). "Their important role in atherogenesis is confirmed in murine knock-out models of CCR2 and CCL2, which show a significant reduction in atherosclerosis formation compared to wild type mice." (PMID 39161593, 2024). "Classical monocytes, on the other hand, are attracted to the atherosclerosis-prone endothelium, targeted by CCL2 on the endothelial surface in a manner reliant on the leukocyte C-C Chemokine Receptor Type 2 (CCR2)." (PMID 39161593, 2024). "In this study, through comprehensive analysis methods, four key genes—CCL3, TNF, CCR2, and CCR5—were identified, having significant impacts on the pathophysiological mechanisms of gout and atherosclerosis." (PMID 39677038, 2024). "We noted a significant upregulation between MYD88 and CCL20 (G60); IFNβ (G90); NF-kB, IL18 (G120); NF-kB, CCR2, IL1b, IL18 (GF120); and CCR2 (GR120) in the thoracic aorta during the inflammatory process of atherosclerosis." (PMID 37298199, 2023). "In the early stage of atherosclerosis, activated endothelial cells secrete monocyte chemoattractant protein-1/C-C chemokine ligand 2 (MCP-1/CCL2), and its receptor C-C Motif Chemokine Receptor 2 (CCR2) is highly expressed on the surface of monocytes." (PMID 36483980, 2022). "Lipidic nanoparticles were reported with a small interfering RNA against C-C chemokine receptor type 2 (CCR2) that reduced inflammatory monocyte recruitment and overall inflammation in ischemia and atherosclerosis." (PMID 35455438, 2022). "Research confirmed that ANW downregulated the expression of chemokine receptors CCR2, CXCR3, and cell adhesion molecules in the arterial vasculature and alleviated the development of atherosclerosis by suppressing inflammation." (PMID 35388303, 2022).